ALB (albumin)
Diseases named in the same sentence as ALB in open-access papers (continued):
Sharing a sentence is not in itself a finding about the gene and the disease.
COVID-19 (continued). "The results showed that the initial albumin on admission was an independent early predictor with a good predictive performance for severe COVID-19." (PMID 33110593, 2020). "The odds of having abnormally low neutrophil count were lower in the HAdV patients than in the COVID-19 patients, but the odds of having higher-than-normal levels of hemoglobin, albumin, APTT, CRP, and procalcitonin were higher in HAdV patients." (PMID 33302983, 2020). "We found that the albumin level was generally decreased in COVID-19 patients and was significantly decreased in patients with severe- illness." (PMID 32555674, 2020). "Regarding the LFTs of COVID-19 positive patients, the most prevalent abnormality was reduced serum albumin level, whereas liver enzymes were mostly normal or marginally raised." (PMID 33194489, 2020). "Albumin and pre-albumin levels have already been described as prognostic factors for COVID-19 severity." (PMID 33260603, 2020). "Further analysis showed that albumin levels were decreased in COVID-19 patients, indicating hypoimmunity following SARS-CoV-2 infection." (PMID 33065551, 2020). "Weighted mean of albumin was found to be lower by 3.28 g/liter (95% CI = 3.05-3.50) in patients with COVID-19 as compared to general population." (PMID 32983698, 2020). "Additionally, severe COVID-19 was associated with increased neutrophil counts (P < .001), C-reactive protein (P < .001), procalcitonin (P = .024) and decreased lymphocyte counts (P = .001), hemoglobin (P < .001), total protein (TP) (P < .001), and albumin (ALB) (P < .001)." (PMID 33157938, 2020). "Among COVID-19 patients, those with concomitant bacterial pneumonia had lower levels of albumin, hemoglobin, and lymphocyte ratio, along with higher levels of procalcitonin, globulin, glucose, urea, white blood cell count, and neutrophil ratio, than patients without bacterial pneumonia." (PMID 41270012, 2025). "Ongoing research supports the potential benefits of serum albumin therapy for COVID-19 patients." (PMID 40699702, 2025). "In addition, serum albumin concentration (2.93 ± 0.4 g/dL) was significantly lower in the critical group compared to the non-COVID-19 group, and this concentration was below the reference normal range (3.5 to 5.5 g/dL)." (PMID 40508859, 2025). "Another recent systematic review and meta-analysis found that ischemic-modified albumin, a marker of oxidative injury, is elevated in COVID-19 patients, while total thiol levels are reduced, especially in critically ill cases, reinforcing redox imbalance as a disease-modifying axis." (PMID 41209585, 2025). "Low serum ALB levels therefore reflect both an ongoing inflammatory process and a catabolic state, which contribute to organ dysfunction and worse clinical outcomes in COVID-19 patients." (PMID 41327060, 2025). "To aid in the early identification of COVID-19 patients at risk for pulmonary bacterial coinfections, we developed a predictive model based on key clinical and laboratory parameters, including PCT, WBC count, glucose, albumin, and age." (PMID 41270012, 2025). "This study investigated the effects of albumin infusion in COVID-19 hypercoagulation patients." (PMID 40699702, 2025). "The IL-15-to-albumin ratio enhanced mortality prediction in hospitalized COVID-19 patients." (PMID 40649865, 2025). "Some of the metabolites, such as acetoacetate and albumin, also differed among COVID-19 patients." (PMID 40399692, 2025). "Albumin and aminotransferase levels of the COVID-19 patients were higher." (PMID 41007672, 2025). "Our results confirmed that COVID-19 is associated with a severe outcome and identified increased levels of ferritin, fibrinogen, and platelets, as well as decreased levels of albumin, as having a negative impact on patient survival." (PMID 39119143, 2024). "Albumin and eGFR levels were lower after COVID-19 than before COVID-19, but the magnitude of the change may be of negligible clinical significance." (PMID 39772028, 2024).
COVID-19 (continued). "The blood markers most strongly associated with 28-day mortality in COVID-19 patients were lowest albumin level, peak neutrophil count, and peak CRP (p < 0.001), while the strongest markers for pneumonia patients were lowest albumin level and age on admission (p = 0.043 and p = 0.001 respectively)." (PMID 39266635, 2024). "Basophils, lymphocytes, albumin and protein levels decreased in severe COVID-19 patients." (PMID 38245638, 2024). "Additionally, the median hemoglobin and albumin levels tended to be higher in the COVID-19 group than in the pre-COVID-19 group (P = .028 and P = .009, respectively)." (PMID 39115263, 2024). "In addition, the decline in serum albumin levels correlated with disease severity and mortality in our COVID-19 cohort." (PMID 38799469, 2024). "Low albumin levels predicted worse outcomes in cancer with COVID-19 in several other studies." (PMID 38633403, 2024). "Serum albumin on admission has been investigated among inpatients with COVID-19." (PMID 39612427, 2024). "Regarding predictors of mortality, our analysis identified that old age, AKI at presentation, increased total leukocyte counts, low platelet counts, decreased albumin levels, and increased LDH levels were significant factors associated with 30-day mortality in patients with COVID-19." (PMID 38639116, 2024). "The reduction in serum albumin is also important in the context of hypercoagulation of COVID-19." (PMID 39456513, 2024). "Moreover, disruption of the BBB as determined by elevated albumin levels in the cerebral spinal fluid and increased fibrinogen deposition in the brains, appears to be common in COVID-19 patients." (PMID 38532784, 2024). "Additionally, reverse MR analysis affirmed the influence of COVID-19 on four blood biomarkers, with two (albumin and total bilirubin) reflecting our observational data trends." (PMID 38549094, 2024). "We suggest that further work may explore if lower albumin levels may be a predictor of COVID-19 reinfection." (PMID 38992084, 2024). "Albumin value was found to be significant in patients who died from COVID-19." (PMID 38371031, 2024). "Patients with COVID-19 show a simultaneous increase in LPS and NOX2 activity associated with a reduction in albumin that may contribute to a hypercoagulation state and eventually increase the thrombotic risk." (PMID 39456513, 2024). "Previous studies of COVID-19 showed that albumin was an important prognostic factor, and that a higher baseline level was associated with a decreased risk of adverse events, such as venous thromboembolism, acute respiratory distress syndrome, ICU admission, and mortality during hospitalization." (PMID 38783947, 2024). "Together, these data suggest that intensive treatment may be necessary for patients with COVID-19 with malignant HDs who have low albumin levels and require oxygen at the time of diagnosis." (PMID 38172385, 2024). "Systemic inflammation markers, CRP/albumin ratio, neutrophil/lymphocyte ratio, and platelet/lymphocyte ratio were significantly higher, while lymphocyte/monocyte ratio was also significantly lower in patients with severe COVID-19 than in healthy volunteers." (PMID 39058886, 2024). "In our model, based on a high level of CRP, increased neutrophil, low lymphocytes, and low albumin, patients with a high level of D-dimer were with a higher mortality, indicating that the measurement of D-dimer is helpful for COVID-19 prediction, which is consistent with previous findings." (PMID 38698064, 2024). "Reduced albumin at admission was an independent risk factor associated with no improvement at follow-up in COVID-19 patients." (PMID 38611597, 2024). "We hypothesized that the lactate/albumin ratio is a better prognostic marker than lactate alone in the prediction of mortality among critically ill patients admitted to the ICU due to COVID-19." (PMID 39685564, 2024).
COVID-19 (continued). "However, when serum albumin was added to the COVID-19 specimens and processed with peripheral blood at a ratio of 1:4, the total number of smudge cells did not decrease." (PMID 38348024, 2024). "As a prospective biomarker, the albumin/globulin (ALB/GLB) ratio (AGR) could be instrumental in risk categorization and management of patients with COVID-19." (PMID 38303719, 2024). "Moreover, patients with COVID-19 had lower bilirubin and higher serum albumin, indicating better liver function." (PMID 39311203, 2024). "This study shows albumin, lymphocytes, platelets and ferritin as factors that may correlate with the severity of COVID-19, and with regard to pro-inflammatory cytokines, the authors found IL-6, IL-10, IL-2 and IL-17 to be elevated in severe patients." (PMID 38807995, 2024). "Also increased urea, enzymes (AST, CK), D-dimers, procalcitonin, ferritin, and IL-6; and decreased GFR, albumin, lymphocytes, and platelets are markers with unfavorable prognosis for COVID-19 in T2D patients during the treatment period." (PMID 38398069, 2024). "Rapid albumin loss has been described in critically ill patients with COVID-19 during the early phase of ICU admission, regardless of outcome." (PMID 39685564, 2024). "Thus, when the information on weight loss and nutritional intake is insufficient, PNI can be applied as a simple index to objectively and effectively reflect the nutritional status of COVID-19 patients based on lymphocyte and albumin values." (PMID 37867496, 2023). "At the biochemical level, COVID-19 patients had decreased serum levels of albumin, alanine aminotransferase (ALT), aspartate aminotransferase (AST), LDH, highly sensitive troponin (hs-troponin), procalcitonin, serum ferritin, procalcitonin, elevated triglycerides, and CRP." (PMID 36851766, 2023). "A study that included 800 hypertensive COVID-19 patients showed that urea nitrogen, albumin, and B/A were all valid predictors of in-hospital mortality, while B/A was a more reliable predictor than urea nitrogen and albumin." (PMID 38114922, 2023). "As a typical nutritional indicator, low albumin levels in patients with COVID-19 may be a marker of excessive consumption due to tissue damage and hypermetabolism." (PMID 37448768, 2023). "Data on changes in albumin levels over the course of severe COVID-19 are limited." (PMID 37810906, 2023). "B. plebeius was found to be positively correlated with albumin, while Lactobacillus salivarius and Bacteroides fragilis were inversely related to albumin, indicating a potential connection between gut microbes and potential organ injury in COVID-19 patients." (PMID 38149007, 2023). "We predicted that, compared to the previous COVID-19 strains, the Omicron could show different emergency patterns of prediction, mainly for TnT and albumin." (PMID 37110348, 2023). "Two months of concurrent training performed at a moderate intensity (according to the RPE scale) promoted significant improvements in lower limb muscle strength, increased albumin concentration, and significantly reduced inflammation in patients after hospital discharge for COVID-19." (PMID 37700761, 2023). "In the examined cohort of COVID-19 patients, statistically significant differences in the level of albumin, urea, potassium, sodium, chloride, direct bilirubin, total protein, troponin, PCT, CK-NAC, and CK-MB were revealed between those who survived and those who died." (PMID 38132876, 2023). "Low albumin levels were still significantly associated with severe COVID-19 after the multivariate analysis among hospitalized COVID-19 patients with or without MAFLD." (PMID 37823314, 2023). "Univariate analysis indicated physical status (PS) score (p = 0.033), PD-L1 expression (p = 0.021), COVID-19 vaccination (p = 0.002), albumin (p < 0.001), fibrinogen (p < 0.001) checked before ICIs treatment were independent prognostic factors for PFS in NSCLC patients with ICIs treatment." (PMID 37679851, 2023).
COVID-19 (continued). "In addition, PLT, RBC, HGB, HCT, MCHC, and albumin were independent protective factors for COVID-19 severity." (PMID 38027038, 2023). "Additionally, some laboratory data were determined for the patients, such as albumin, lymphocytes, platelets, and ferritin; these factors are of interest for their possible correlation with the severity of COVID-19." (PMID 36835858, 2023). "However, K and albumin levels were significantly lower in the COVID-19 patients compared to the control group (P<0.03 and 0.02 respectively)." (PMID 37362525, 2023). "Notably, the decline, nadir and recovery of albumin levels in patients with COVID-19 were more pronounced compared with those patients with illnesses of non-COVID-19 etiology." (PMID 37810906, 2023). "While diagnostic algorithms based on pre-test probability assessment such as the Padua score are widely used for predicting the risk of PE also before the COVID-19 pandemic, the ADA (Age, D-Dimer, Albumin) score has been recently validated in COVID-19 patients." (PMID 37238955, 2023). "Consistent with previous findings, routine CSF parameters of patients with COVID-19 showed normal levels with only the albumin CSF/serum ratio (median 10.24, range 5–43.6, normal ratios are from 4 to 9 increasing linearly with age) being slightly higher than normal." (PMID 36759861, 2023). "Different from the initial stage of the pandemic, older age, chest tightness, elevated NLR, decreased albumin level and GGO in radiological findings were identified as severity risk factors, instead of mortality risk factors for COVID-19 patients in the very late stage of the pandemic." (PMID 37841011, 2023). "By identifying COVID-19 patients at increased risk of disease severity and mortality, the BUN to albumin ratio may help clinicians make more informed clinical decisions, such as earlier initiation of intensive care or more aggressive treatment strategies." (PMID 38074058, 2023). "Noteworthy, in critical COVID-19 patient groups, U-CysLT were also associated with hepatic injury/dysfunction, being positively correlated with AST and ALP and inversely correlated with albumin." (PMID 36617343, 2023). "Reason explaining the low albumin concentration could be related to the characteristic inflammatory state of COVID-19, which due to vascular permeability could result in the extravasation of serum albumin into the interstitial fluid." (PMID 37497238, 2023). "Thus, in COVID-19, the condition is strongly related to widespread inflammation, and the reduction of albumin concentration has been well-reported." (PMID 37867496, 2023). "Similarly, we found the median serum albumin level to be 3.08 g/dl for all hospitalized COVID-19 patients and a value of 2.74 g/dl for patients who died." (PMID 36116079, 2023). "Their findings indicated that this allele exhibited a tendency not only to be associated with protection against COVID-19 but also with lower levels of C-reactive protein, despite higher ALT and lower albumin levels in severe COVID-19 patients of European ancestry." (PMID 37632067, 2023). "COVID-19-positive hemodialysis patients were more likely to experience weight loss and exhibit reduced albumin levels compared to those without COVID-19 (p < .05)." (PMID 37501590, 2023). "Notably, the QMP albumin-based strategy offers promising research and clinical development prospects, which extends beyond COVID-19 and offers innovative frameworks for a range of diseases that require long-acting, non-invasive mucosal delivery." (PMID 38077689, 2023). "However, the levels of total protein, albumin, and platelets were significantly (P<0.01) lowered in COVID-19 patients compared to the control group." (PMID 37540679, 2023). "[Albumin] is significantly decreased in severe cases of COVID-19 patients, including those requiring intensive care, by 10–20% and is considered an independent death risk factor linked to serious effects of the virus, such as coagulopathy, vascular disease and lung injury." (PMID 37486805, 2023).
COVID-19 (continued). "Prior to COVID-19, PNI was emphasized to be associated with nutritional status and the response of the immune system of patients, which was based on blood lymphocyte count and albumin level." (PMID 37867496, 2023). "Based on this information, we consider that the combination of procalcitonin and albumin parameters, which reflect both inflammatory and nutritional status, may increase the estimation of COVID-19 disease severity." (PMID 36950410, 2023). "However, due to the high number of COVID-19 patients showing albumin levels below 3.5 g/dL (597 patients), it is difficult to assume that all these patients had liver dysfunction." (PMID 35160039, 2022). "Albumin is a negative acute-phase reactant, and the association of reduced albumin levels with COVID-19 severity has been observed in many studies." (PMID 35464560, 2022). "Albumin is prognostic for hospitalized COVID-19 patients, and its administration might have an anticoagulant effect, although further studies are needed to explore this." (PMID 35887713, 2022). "Furthermore, COVID-19 lowered albumin levels in both third trimester and severe second trimester women." (PMID 36138463, 2022). "One of them is why serum albumin levels are reduced in some COVID-19-infected patients." (PMID 35160039, 2022). "Several researchers suggested at the beginning of the COVID-19 pandemic that oxidized albumin may be “an opportunity for diagnoses or treatment of COVID-19” and “a positive predictor of mortality”." (PMID 36077496, 2022). "Hepatic injury in COVID-19 patients can be assessed using liver biochemical tests: serum albumin, cholestasis markers-bilirubin, gamma-glutamyl transferase (GGT), alkaline phosphatase (ALP), liver transaminases-aspartate aminotransferase (AST/TGO), and alanine aminotransferase (ALT/TGP)." (PMID 36676691, 2022). "ALB levels in blood can be used as a biomarker for measuring COVID-19 severity." (PMID 35438176, 2022). "Low albumin patients were among those who contracted COVID-19 during the 6-month follow-up." (PMID 35327438, 2022). "In addition, when compared to healthy controls, albumin levels were significantly lower in moderate and severe COVID-19 patients (p < 0.001)." (PMID 36298501, 2022). "Serum albumin levels were predictive of adverse outcomes in patients with confirmed COVID-19." (PMID 35165642, 2022). "The most common laboratory abnormalities identified in patients with COVID-19 include decreased albumin and lymphocyte count and elevated C-reactive protein (CRP), lactate dehydrogenase (LDH), erythrocyte sedimentation rate (ESR), aspartate transaminase (AST), and alanine transaminase (ALT)." (PMID 36570594, 2022). "In addition, some studies revealed the role of albumin in COVID-19 prognostication reflecting both possible liver damage, inflammation and the nutritional status of patients." (PMID 35350866, 2022). "Models tested on a smaller group of patients n = 401, which included albumin, turned out to be a better indicator of COVID-19 severity than the NLR for all endpoints and, along with TBIL, the best model to predict the risk of death, which aligns with Weber and colleagues’ findings." (PMID 35956107, 2022). "A lower level of serum albumin was seen in critically ill COVID-19 patients with poor prognosis." (PMID 35865866, 2022). "Besides, a strong positive relationship between FT3 and ALB had been found, with a distinct decline in the plasma ALB in the COVID-19 patients." (PMID 35721727, 2022). "The present study was designed to confirm whether LDH/albumin ratio can be used as an independent prognostic factor in patients with severe ARDS due to COVID-19." (PMID 36197158, 2022). "The measurement of both vitamin D and serum albumin levels on COVID-19 patients’ admission, and their combined evaluation, provides a simple prognostic tool that could be employed to guide prompt clinical decisions." (PMID 35182287, 2022).